VDR (vitamin D receptor)
Diseases named in the same sentence as VDR in open-access papers (continued):
Sharing a sentence is not in itself a finding about the gene and the disease.
cancer (continued). "The cumulative OR for the “A” allele of the ApaI VDR polymorphism in the tobacco-related cancer group was 1.27 (1.01–1.60 95% CI)." (PMID 31690771, 2019). "VDR gene polymorphisms have been suggested to be correlated with the risk of different cancers due to their role in the modulation of the antiproliferative effect of vitamin D22." (PMID 31690771, 2019). "We found a significant relationship between tobacco-related cancers and the occurrence of the “t” allele in the TaqI polymorphism of VDR." (PMID 31690771, 2019). "In our study, we focused on the effect of four VDR polymorphisms and we assessed the impact on the risk of developing cancers of the respiratory system and esophagus." (PMID 31690771, 2019). "As with the main analysis, higher VDR expression was associated with improved overall survival and cancer-specific survival, and the magnitude of associations were strengthened." (PMID 30344947, 2018). "It has been shown that VDR polymorphism is associated with a risk of cancer, with some genetic variants increasing while others decrease the risk." (PMID 29951549, 2018). "Third, constitutively active mutations of the Ras oncogene found in many cancers suppress VDR expression in tumors." (PMID 29657326, 2018). "The deficiency of VDR is associated with an increased cancer incidence, and there are about 200 SNPs." (PMID 30008463, 2018). "Another kinase involved in the regulation of PTMs of VDR and in clear relationship to cancer is ATM (ataxia telangiectasia mutated)." (PMID 28427151, 2017). "The association of single nucleotide polymorphisms (SNPs) in VDR (ApaI [rs7975232], BsmI [rs1544410], FokI [rs10735810], TaqI [rs731236] and cancer risk has been reported, yet the results were inconclusive." (PMID 28489590, 2017). "In our meta-analysis, we found evidence of an association between the VDR gene variants with functionally characterised effects and cancer outcome." (PMID 28301870, 2017). "VDR function has been investigated in developmental studies as well as its association with various diseases, cancer, and carcinogen-induced tumorigenesis." (PMID 29272316, 2017). "VDR signaling is pleotropic, being implicated in calcaemic function, antibacterial actions, growth control, immunomodulation and anti-cancer actions." (PMID 28166722, 2017). "Meta-analyses have assessed the association between VDR polymorphisms and cancers, showing that variants of the VDR or higher levels of VDBP were associated with an increased risk for certain types of cancer." (PMID 28390010, 2017). "Despite the large body of literature supporting roles for the VDR in various cancers, only one phenotype associated SNP related to cancer and this suggests that genetic variation does not impact VDR signaling in cancer phenotypes to a significant extent." (PMID 28166722, 2017). "Research on these have individually reported 1,600–6,200 VDR-specific binding sites that were significantly enriched near autoimmune- and cancer-associated genes." (PMID 28377587, 2017). "As a result, roles for VDR function and dysfunction have been implicated in a wide range of complex phenotypes including autoimmunity, diabetes, cardiac health and cancer." (PMID 28166722, 2017). "Most VDR gen polymorphisms were identified since 1997, and about six gen polymorphisms were found to be associated with cancers." (PMID 28206978, 2017). "Gandini and colleagues reviewed 79 studies involving more than 52,000 different cancer cases and 62,000 controls to identify relevance of VDR BsmI, FokI, ApaI and TaqI polymorphism for various cancers and found BsmI, FokI and TaqI to be associated with CRC." (PMID 27309378, 2016). "Another evidence comes from studies on animal models showing that deletions in the VDR gene were associated with an increased cancer risk, and that injection of chemical analogues of vitamin D led to a reduction in tumor incidence and size." (PMID 27058533, 2016).
cancer (continued). "Polymorphisms in VDR gene have been significantly associated with various cancers including prostate, breast, skin and colorectal." (PMID 27309378, 2016). "Population-based studies revealed an importance of VDR gene polymorphism in cancer biology and that selected VDR polymorphism altered susceptibility and prognosis of different tumors." (PMID 26501255, 2015). "In fact, VDR polymorphisms have been identified in various diseases, such as cancer or cancer risk, asthma, and kidney diseases." (PMID 26000293, 2015). "Recently, the association between the common VDR gene variant rs7968585 and risk of a composite health outcome including hip fracture, MI, cancer, and mortality has been reported in subjects with low serum 25(OH)D levels." (PMID 26699871, 2015). "Many epidemiological studies have evaluated associations between VDR variants and various types of cancer including those of the breast, colorectal region, ovary, and prostate." (PMID 25887475, 2015). "Biological and epidemiological data have revealed the protective functions of vitamin D against ovarian, breast, colorectal, gastric, liver, prostate, and nonmelanoma skin cancers and the potential role of VDR gene polymorphisms and risk of cancer." (PMID 26000308, 2015). "The vitamin D receptor (VDR) mediates the major cellular activities of vitamin D and regulates various signaling pathways implicated in cancer development and progression." (PMID 25887475, 2015). "Polymorphisms of the VDR gene have been associated with several forms of cancer and other chronic diseases." (PMID 24297042, 2014). "VDR polymorphisms have been associated, both positively and inversely, with risk of cancer depending on the type of cancer, polymorphism, and other factors such as sun exposure or circulating vitamin D levels." (PMID 25255691, 2014). "Multiple studies have associated VDR polymorphisms with cancer risk and progression, particularly for susceptibility to lung and ovarian cancers." (PMID 24557774, 2014). "About the mechanism of the VDR gene polymorphism and cancer relationship, it is now widely recognized that 1, 25 (OH) 2D3 and its analogs fix tumor cell growth cycle in the G1 phase via VDR, thereby inhibiting tumor cell proliferation." (PMID 24755043, 2014). "Several population based studies indicated that VDR gene polymorphisms are associated with human cancers." (PMID 23705897, 2013). "VDR is expressed in most tissues in the human body, and vitamin D plays an important role in decreasing the risk of many chronic illnesses, cancers, autoimmune diseases, infectious diseases, and cardiovascular disease." (PMID 24202445, 2013). "Among ten studies which examined the relationship between VDR polymorphisms and cancer prognosis, five found significant associations and five did not." (PMID 23533810, 2013). "Genetic studies have investigated the possible association between various histotypes of cancer and the detection of specific SNPs of the VDR gene (VDR-SNPs)." (PMID 23761840, 2013). "Numerous studies have demonstrated that polymorphisms of the VDR gene have important implications in VD signaling and are associated with various malignancies, including cancer of the colon, breast, kidneys and prostate." (PMID 23761840, 2013). "The low levels of VDR in late stage carcinomas were attributed to failure of the antiproliferative effect of vitamin D and subsequent loss of VDR expression." (PMID 23346460, 2012). "Although there are many studies investigating associations between serum 25(OH)D levels/VDR polymorphisms and risks of developing cancer, only a few studies have examined the impact of serum 25(OH)D levels on the prognosis of patients with cancer." (PMID 22242137, 2011). "Several studies have examined variation in VDR in search for an association with different types of cancer." (PMID 21358824, 2011). "Four VDR SNPs in two haplotype block regions were shown to significantly increase cancer risk among men with low UV exposure." (PMID 20049159, 2010).
cancer (continued). "While no reports to date have investigated the association between RCC risk, dietary intake of vitamin D or calcium rich foods, and vitamin D gene variants, results have been reported for VDR SNPs and other cancers." (PMID 20049159, 2010). "We performed a meta-analysis on the association between the two most studied VDR polymorphisms (FokI and BsmI) and cancer at any site." (PMID 22276021, 2009). "The importance of dietary calcium, vitamin D, energy and fat in modifying the association between VDR genotype and cancer risk has been shown repeatedly." (PMID 22276021, 2009). "The differences of VDR gene polymorphism between cancer cases and controls were determined by PCR-RFLP, examiming FokI (exon 2), BsmI, Tru9I, ApaI (intron 9), and TaqI (exon 9)." (PMID 19961572, 2009). "Only when the whole gene can be examined along with associated regulatory elements can we develop a clearer picture of the underlying biology that consistently links the VDR gene to cancer risk." (PMID 18067661, 2007). "Moreover, low VDR expression measured by IHC staining was associated with aggressive characteristics in different cancers." (PMID 40008182, 2025). "Additionally, both RARA and VDR are classified as nuclear receptors that have been linked to cancer." (PMID 40334012, 2025). "Additionally, the 1,25(OH)2D/VDR signalling axis plays a pivotal role in modulating the inflammatory pathways associated with cancer by downregulating cyclooxygenase-2 (COX-2), prostaglandin synthesis, and NF-kB signalling." (PMID 40351788, 2025). "The single-nucleotide polymorphisms (SNPs) of VDR rs2228570, rs731236 and rs7975232, may substantially influence variations in bone mass and cancer susceptibility." (PMID 41561541, 2025). "They found increased levels of pro-cancer lncRNAs in these cells, suggesting that loss of VDR creates an imbalance that may predispose keratinocytes to tumorigenesis." (PMID 40724881, 2025). "The VDR ApaI C/A polymorphism might serve as a valuable indicator for determining cancer diagnosis and prognosis." (PMID 39861482, 2025). "Some microbial-generated bile acids may activate vitamin D receptor (VDR)-mediated protective pathways in gut-associated cancers, but under WD, the shift favors pro-carcinogenic metabolites." (PMID 40944286, 2025). "RARB and VDR are specific types of these receptors that have been implicated in cancer." (PMID 40334012, 2025). "Significant associations have been identified with specific VDR polymorphisms, such as Fok1, Bsm1, Taq1, and Apa1, suggesting that VDR genetic variation may modulate cancer risk." (PMID 39683528, 2024). "Increased expression of VDR was associated with either good or poor prognosis in 13 cancer types." (PMID 38639057, 2024). "VDR gene RFLPs were also associated with an increased risk of 19 different types of cancers." (PMID 39335182, 2024). "VDR stands for vitamin D receptor and has been associated with cancer development." (PMID 38779099, 2024). "In addition, the positive correlations between VDR expression and the expression of cancer-associated fibroblast, macrophage, and neutrophil markers are experimentally verified in PTC." (PMID 38639057, 2024). "As far as we know, this is the first pan-cancer study to analyze VDR expression and the association with clinical outcomes, immune infiltration, tumor microenvironment and gene set enrichment based on online databases and R software across 33 types of human cancers." (PMID 38639057, 2024). "Additionally, studies have explored the potential interactions between VDR polymorphisms and cancer-related phenotypes, including tumor aggressiveness, response to treatment, and clinical outcomes." (PMID 39683528, 2024). "The VDR gene polymorphisms examined in this meta-analysis, such as FokI rs2228570 and TaqI rs731236, are not specific to GC, as they have been associated with various other cancer types as well." (PMID 39213223, 2024).
cancer (continued). "Dysfunction of VDR and vitamin D3 deficiency can cause poor bone development and health, as well as increase the risk of many chronic diseases, including type 1 diabetes, rheumatoid arthritis, Crohn’s disease, infectious diseases, and cancer." (PMID 37555855, 2024). "Furthermore, the function of VD-mediated activation in carcinogenesis is becoming more widely acknowledged, since numerous researchers have examined the implications of VDR genetic variants in various forms of cancer." (PMID 38125732, 2024). "VDR and cancer risk have recently been the focus of a number of studies." (PMID 35637613, 2023). "Several SNPs of the VDR gene have been associated with cancer, including CRC." (PMID 37371861, 2023). "Importantly, the relationships between specific VDR polymorphisms and cancer types remain ambiguous." (PMID 37299554, 2023). "Vitamin D receptor (VDR) polymorphisms might increase the risk of several types of cancer (breast, ovarian, colorectal)." (PMID 37189693, 2023). "The VDR gene encodes the nuclear hormone receptor for vitamin D3, which is a member of the superfamily involved in mineral metabolism, and in energy metabolism, muscle hypertrophy, immune response, and cancer." (PMID 36672947, 2023). "Other genetic polymorphisms in diverse CYP-enzymes can lead to remarkably reduced conversion to calcitriol, and genetic variations in the vitamin D receptor have been linked to increased incident of hip fracture, myocardial infarction, cancer and mortality overall." (PMID 36726354, 2022). "The logistic regression model adjusted for smoking and family history of cancer revealed that in the genotypic model carriers of the VDR BsmI rs1544410-AA genotype were associated with a lower risk of developing NSCLC compared to the GG genotype (p = 0.0377; OR = 0.51; CI95% = 0.27–0.95; AA vs. GG)." (PMID 36364930, 2022). "Similarly, the seed genes SRC and VDR in two functional modules identified in the PPI network were also closely associated with cancer progression." (PMID 35273218, 2022). "Although polymorphisms in the vitamin D receptor, vitamin D binding protein, and vitamin D binding protein genes have been linked to a variety of cancers, the prognostic value of VDR rs2228570 and rs1544410 and VDBP rs7041 polymorphisms in PCa is unknown." (PMID 36017197, 2022). "Such target modulation was also reflected in cell cycle progression and clonogenic survival, further supporting the notion that ERRα‐ERα cross talk regulated sensitivity to calcitriol in both cancer models, while ERRα caused deregulation of VDR genomic action mostly in the basal‐like model." (PMID 34003583, 2022). "In this study, we show that lifestyle factors, i.e., moderate to high levels of physical activity combined with the intake of vitamin D supplements, affect DNA methylation in genes regulating the vitamin-D-receptor pathway and pathways associated with cancer initiation and development." (PMID 35879377, 2022). "However, only a few of them, including FOKI, BsmI, ApaI, and TaqI, have potential functions to affect the expression of VDR genes and are associated with cancer risk." (PMID 36440356, 2022). "A further point of uncertainty is whether these receptors persist after the VDR in advanced cancer, loss of signalling being central to our argument about a possible deleterious effect of vitamin D3 supplements in advanced cancer." (PMID 35445563, 2022). "Therefore, it has been suggested that the underlying mechanism comprises vitamin D promotion of VDR/β-catenin binding in cancer cells, which contributes to the inhibition of the nuclear translocation of β-catenin." (PMID 36233580, 2022). "The NRs associated with cancers include the retinoic acid receptors (RARs), the retinoid X receptors (RXRs), the peroxisome-proliferator-activated receptor γ (PPARγ), and the vitamin D receptor (VDR)." (PMID 35631448, 2022).
cancer (continued). "Reversely, decreased VDR expression, found in advanced colorectal and other neoplasms, suggests that loss of VDR may contribute to cancer progression." (PMID 36014865, 2022). "While associations between vitamin D or VDR and cancer have been shown in multiple studies, few studies exist that rigorously test whether lack of vitamin D or its receptor directly affects intestinal cancer." (PMID 35662320, 2022). "The fact that an inverse association between VDR expression and tumor aggressiveness has been found suggests that VDR may be a target subjected to downregulation or ablation along the cancer progression cascade into more aggressive stages." (PMID 35884356, 2022). "Many studies have analyzed the association of VDR SNP with cancer, such as breast cancer (FokI, BsmI, and ApaI), prostate cancer (FokI, BsmI, and TaqI), colorectal cancer (FokI, BsmI, and TaqI), and skin cancer (FokI, BsmI, and TaqI), but there are still controversies." (PMID 36440356, 2022). "The vitamin D receptor (VDR) is linked to cancer by an increasing body of evidence." (PMID 35884356, 2022). "Considering that VDR polymorphisms may affect the risk of cancer at multiple body sites and that an effect on NMSC risk cannot be ruled out a priori, we recommend that more studies are conducted in this research area." (PMID 34638299, 2021). "Multivariate Cox regression, adjusted for family history of cancer, showed that the VDR rs11568820 polymorphism was the only independent factor associated with OS in patients with resected NSCLC (p = 0.0129; HR = 7.43; CI95% = 1.53–36.15) (Plikelihood ratio test = 0.04)." (PMID 34836039, 2021). "Most convincing data from preclinical studies show how VDR can modulate the transcriptome in tumor cells, shaping micro RNA expression in a onco-protective way, and how VDR polymorphisms could increase cancer risk." (PMID 34067977, 2021). "The VDR/RXR pathway has been implicated both in cancer and cardiovascular diseases." (PMID 34944912, 2021). "However, the underlying mechanisms of diverse VDR gene polymorphism in all human cancers remains to be further investigated." (PMID 33732250, 2021). "There are several reports linking vitamin D receptor genotype with cancer risk and mortality, which could explain the variability in the effect of VDS." (PMID 34579164, 2021). "Further studies to determine whether VDR transcript variants are clinically relevant in breast and other cancers are warranted." (PMID 34950835, 2021). "Vitamin D receptor (VDR) deficiency is associated with cancer, infection, and chronic inflammation." (PMID 34375154, 2021). "Vitamin D receptor knockout mice have a tendency to cause infection, cancer, and inflammation." (PMID 33352905, 2020). "VDR is a crucial mediator of the cellular effects of vitamin D. A vast amount of information has been collected over the years regarding the association of VDR polymorphisms with the susceptibility of individuals to suffer from different diseases, such as cancer." (PMID 33255834, 2020). "It has been hypothesized that a less-active VDR could be associated with either an increased susceptibility to cancer risk or a more aggressive disease." (PMID 33255834, 2020). "In fact, VDR downregulation is associated with a poor prognosis and cancer progression." (PMID 33634029, 2020). "In addition, epigenetic marks can reduce sensitivity to vitamin D metabolites in clinical trials by increased methylation of VDR promoter and associated VDR expression in cancer." (PMID 33291213, 2020). "The Fok1 T allele could decrease VDR transcription and translation efficacy which was reported to reduce anti-carcinogenic properties of calcitriol and contributes to an increased cancer susceptibility." (PMID 33112551, 2020). "The aim of this study was to determine whether select VDR polymorphisms may be risk factors in tobacco-related cancers." (PMID 31690771, 2019).